SIRT5 (sirtuin 5)
Diseases named in the same sentence as SIRT5 in open-access papers (continued):
Sharing a sentence is not in itself a finding about the gene and the disease.
colitis (9 papers, 2018 to 2025). Inflammation of the colon. "SIRT5-deficient mice are prone to dextran sulfate sodium (DSS)-induced colitis, which is associated with high PKM2 succinylation and IL-1β production due to SIRT5 deficiency." (PMID 37483618, 2023). "We previously observed that Sirt5 KO mice were highly susceptible to DSS-induced colitis." (PMID 32953892, 2020). "We also found that supplement of IFN-γ inhibited cell viability of mouse colon cancer cells CT26.WT, implying that IFN-γ secreted from activated T cells was partly involved in the suppressed progression of colitis-associated colorectal tumorigenesis in Sirt5 KO mice." (PMID 32953892, 2020). "In that study, SIRT5 deficiency protected from DSS-induced colitis." (PMID 30515162, 2018). "The study revealed that Sirt5 KO mice with induced colitis exhibited increased levels of PKM2 in the dimer form." (PMID 33503959, 2021). "In this work, we found that Sirt5 knockout mice were resistant to AOM and DSS-induced colitis-associated colorectal tumorigenesis and the level of IFN-γ in their tumor microenvironment was higher." (PMID 32953892, 2020). "SIRT5 protects from cardiac dysfunctions and dextran sulfate sodium-induced colitis and promotes or restricts cancer growth depending of the context." (PMID 30515162, 2018). "Recently, the relationship between PKM2 and SIRT5 was confirmed to prevent colitis in mice." (PMID 34898024, 2022). "An anti-inflammatory protective role of Sirt5 was reported in a DSS-induced colitis mouse model." (PMID 35296782, 2022). "Likewise, activation of PKM2 using TEPP-attenuated Sirt5-deficiency-mediated IL-1β upregulation in LPS-stimulated macrophages in vitro and in dextran sulfate sodium (DSS)-induced colitis in mice." (PMID 33503959, 2021). "SIRT5 deacetylates Lys351 of TRIM21, inhibiting the production of IL-1β and preventing colitis." (PMID 39979670, 2025). "SIRT5 desuccinylates and activates SOD1 to eliminate ROS, desuccinylates and activates PKM2 to block macrophage IL-1β production and prevent DSS-induced colitis, and desuccinylates and activates SHMT2 to drive cancer cell proliferation." (PMID 34930316, 2021). "Besides, SIRT5 desuccinylates K311E of PKM2, promotes its nuclear entry and binds to the promoter of the IL-1β gene to form a PKM2-HIF1α complex, reduces IL-1β production, and inhibits the pro-inflammatory response of macrophages in colitis." (PMID 39979670, 2025). "Lipopolysaccharide-induced polarization of pro-inflammatory macrophages biases tripartite-motif protein (TRIM21)-SIRT5 interactions toward activation of TRIM21 and degradation of SIRT5, leading to increased interleukin-1beta (IL-1β) production in vitro and in vivo, thereby aggravating colitis." (PMID 39979670, 2025). "We previously reported that SIRT5 could suppress IL-1β production and proinflammatory responses in macrophages by regulating PKM2 succinylation and its activity and finally alleviated dextran sulfate sodium- (DSS-) induced colitis in mice." (PMID 32953892, 2020).
Parkinson disease (9 papers, 2012 to 2025). A progressive degenerative disorder of the central nervous system characterized by loss of dopamine producing neurons in the substantia nigra and the presence of Lewy bodies in the substantia nigra and locus coeruleus. "In a Parkinson’s disease mouse model induced by oxidative stress, SIRT5 deficiency resulted in severe neuronal degeneration and motor deficits, whereas SIRT5 knockout mice showed no significant phenotype under normal physiological conditions." (PMID 40799515, 2025). "However, more recent studies have found counter evidence showing that SIRT5 depletion causes mitochondrial dysfunction, expression does not increase with Alzheimer’s progression, and can only be linked to Parkinson’s via an autophagic degradation of SIRT5 itself." (PMID 37900096, 2023). "Furthermore, polymorphisms in the promoter region of SIRT5 gene have been associated with the development of premature aging in amygdala region of brain, suggesting the possible involvement of SIRT5 promoter polymorphisms in the incidence of Parkinson’s disease." (PMID 25907989, 2015). "After preliminary links were formed between SIRT5 abundance and incidence of Alzheimer’s, cancer, and Parkinson’s disease, the door of excitement blew open for a rash of new peptide and small-molecule inhibitors." (PMID 37900096, 2023). "Although SIRT5 has deacetylase activity, it is known that it has more robust activities as desuccinylase, demalonylase, and deglutarylase in several human diseases, such as cancer, Alzheimer’s, and Parkinson’s disease." (PMID 34445236, 2021). "In support of such a hypothesis, Sirt5, in particular, has been reported to act as a neuroprotective agent against motor deficit and dopaminergic degeneration in the MPTP (1-methyl-4-phenyl-1,2,3,6-tetrahydropyridine)-induced mouse model of Parkinson’s disease." (PMID 27763519, 2016).
ischemia (8 papers, 2016 to 2025). A hypoperfusion of the BLOOD through an organ or tissue caused by a PATHOLOGIC CONSTRICTION or obstruction of its BLOOD VESSELS, or an absence of BLOOD CIRCULATION. "As Tat‐SIRT5‐CTM exerts neuroprotective effects against ischemia when injected after reperfusion, it is also important to assess its effect when administered prior to reperfusion." (PMID 38093788, 2023). "In conclusion, the results provided direct experimental evidence supporting a possible cardio-protective role of SIRT5 in response to acute ischemia." (PMID 34368135, 2021). "Exposure of hPTECs to OND revealed that SIRT5 expression is regulated by ischemia, a finding that is consistent with our observation in a mouse IRI model." (PMID 34330933, 2021). "Although not an ideal comparison, these regions appear comparable as they display a similar pattern and intensity of SIRT5 expression and are both protected from ischemia by PKCε in vivo." (PMID 29440987, 2018). "To explore the potential role of SIRT5 in PKCε-mediated protection, we compared WT and SIRT5−/− mice by employing both in vitro and in vivo ischemia paradigms." (PMID 27435822, 2016). "SIRT5 regulates the balance between mitochondrial and peroxisomal FAO in proximal tubular epithelial cells, and SIRT5 deficiency appears to be protective by increasing peroxisomal FAO to protect against injury in ischemia-induced or cisplatin-induced AKI." (PMID 35517820, 2022). "It enhanced SIRT5-mediated SDHα desuccinylation and the GSH/GSSG ratio, while reducing SDHA activity, thereby mitigating succinate accumulation during ischemia and decreasing succinate consumption during reperfusion." (PMID 41260100, 2025).
pancreatic cancer (8 papers, 2019 to 2025). "The loss of SIRT5 regulates Glutamine Metabolism and Glutathione Metabolism and Pyrimidine Metabolism promotes pancreatic cancer." (PMID 36568393, 2022). "Regarding SIRT5 activators, MC3138, a selective SIRT5 activator, mimicked the effects of SIRT5 overexpression-mediated deacetylation and desuccinylation in pancreatic cancer cells, leading to reduced levels of metabolites such as glutamine and glutamate." (PMID 39944690, 2025). "SIRT5 plays a multifaceted role in cellular metabolism and is emerging as a key regulator in various cancers, including pancreatic cancer." (PMID 39682281, 2024). "SIRT5, another critical regulator of metabolic processes in pancreatic cancer, modulates glutamine and glutathione metabolism, crucial for sustaining the tumor’s metabolic demands." (PMID 39682281, 2024). "Treatment of pancreatic cancer cells with MC3138 mimicked the deacetylation effect mediated by SIRT5 overexpression with decreased levels of metabolites such as glutamine and glutamate." (PMID 37627630, 2023). "In pancreatic cancer, dysregulated metabolic pathways are critical for tumor growth and survival and SIRT5 may contribute to the adaptation of cancer cells to the nutrient-deprived tumor microenvironment." (PMID 39682281, 2024). "The paucity of research highlights the urgent need for further investigations of SIRT5’s function, as its modulation could present a novel therapeutic strategy by disrupting the metabolic dependencies that sustain pancreatic cancer cells." (PMID 39682281, 2024). "For instance, SIRT1 and SIRT7 were reported to promote pancreatic cancer progression, while SIRT2, SIRT4, SIRT5, and SIRT6 seem to play a tumor suppressor role." (PMID 41391757, 2025). "Given that SIRT5 expression is downregulated in human and mouse pancreatic ductal adenocarcinomas, the application of MC3138 in pancreatic tumors showed inhibitory effects on proliferation." (PMID 39944690, 2025). "Since SIRT5 is downregulated in human and murine pancreatic ductal adenocarcinoma (PDAC), we used MC3138 in cells and organoids of pancreatic tumors, showing an inhibition of proliferation." (PMID 37627630, 2023). "Since knockout of SIRT5 has been reported to promote the KRASG12D-driven PDAC progression in the KPC mouse model, we mainly focused our study on the regulation of SIRT3 by KRASG12D and its potential role in KRAS-driven pancreatic cancer development." (PMID 41391757, 2025). "While the roles of SIRT2, SIRT4, and SIRT5 in pancreatic cancer progression are evident, their utility as biomarkers is not yet fully established." (PMID 39682281, 2024).
colon cancer (7 papers, 2019 to 2025). "Since IBD is an important risk factor for the development of colon cancer, we aimed to examine whether SIRT5 could influence CAC tumorigenesis." (PMID 32953892, 2020). "Citrate synthase (CS), the first rate-limiting enzyme of the TCA cycle, upregulates its activity after desuccinylation by SIRT5 at K393 and K395, promoting colon cancer cell proliferation and migration." (PMID 39979670, 2025). "To investigate the downstream mechanisms by which SIRT5 regulates the proliferation and glycolysis of colon cancer cells, we conducted a pathway enrichment analysis on differentially expressed genes obtained from LEV-treated Caco-2 cells." (PMID 39110260, 2024). "RAD51C, RFC4, and SIRT5 exhibited a low differential expression in Caco-2 cells treated with LEVs but a high differential expression in TCGA colon cancer tissue samples." (PMID 39110260, 2024). "The results above indicate that LEVs can potentially impede the proliferation of colon cancer cells and alter glycolysis metabolism through downregulating SIRT5 expression." (PMID 39110260, 2024). "In colon cancer cells, CS has been shown to interact with SIRT5, a nicotinamide adenine dinucleotide (NAD)+-dependent deacetylase." (PMID 37601653, 2023). "We then examined the development of colon tumors and found that Sirt5 KO mice developed significantly decreased numbers of tumors, compared with WT mice." (PMID 32953892, 2020). "SIRT5 demalonylates K179 of SDHA, downregulating its activity, leading to succinate accumulation and activation of the ROS scavenging enzyme thioredoxin reductase 2 (TrxR2), causing colon cancer cell resistance to rituximab." (PMID 39979670, 2025). "Research has also found that SIRT5 interacts with CS, and SIRT5 removes succinyl groups from CS at the evolutionarily conserved residues K393 and K395, promoting the proliferation and migration of colon cancer cells." (PMID 40557149, 2025). "Therefore, we conducted a further investigation to determine if LEVs regulate the expression of SIRT5 and affect the proliferation of colon cancer cells." (PMID 39110260, 2024). "Based on the results above, we hypothesize that SIRT5 could serve as a crucial target gene in regulating colon cancer progression by LEVs." (PMID 39110260, 2024).
colon cancer (continued). "Additionally, the correlation between SIRT5 and the prognosis of colon cancer patients was further confirmed through bioinformatics analysis." (PMID 39110260, 2024). "SIRT5 dessucinylates CS, regulating its enzymatic activity, whereas hypersuccinylation of CS reduces its enzymatic activity and inhibits the proliferation and migration of colon cancer cells." (PMID 37601653, 2023). "In order to determine whether IFN-γ could be derived from colorectal cells, we transfected Sirt5-specific siRNA or control siRNA to two mouse colon cancer cell lines, CT26.WT and MC38." (PMID 32953892, 2020). "Next, we confirmed the expression of RAD51C, RFC4, SIRT1, SIRT5, and SMAD3 genes in different colon cancer cell lines." (PMID 39110260, 2024). "We found that whether Sirt5 was knocked down or not, the mRNA level of IFN-γ in colon cancer cells was too low to be determined and IFN-γ in the supernatant was not detectable, either." (PMID 32953892, 2020).
diabetes (7 papers, 2011 to 2022). "Some modifications by hypertension and diabetes were also observed in the association of SIRT3, SIRT5 and UCP5 genetic variants with carotid plaque." (PMID 22087257, 2011). "Some interactions with a nominal p≤0.01 were found between sex and SNPs in the UCP1 and UCP3 gene; between smoking, diabetes, hypertension and SNPs in UCP5 and SIRT5; and between SNPs in the UCP5 gene and the UCP1, SIRT1, SIRT3, SIRT5, and SIRT6 genes in association with plaque phenotypes." (PMID 22087257, 2011). "Previous studies have shown that circ-KLHL8 could be used as a candidate biomarker for the diagnosis of diabetes and promote epithelial healing, regulating endothelial cell apoptosis, survival, and maintaining endothelial function through activating the miR-212-3p/SIRT5 signaling pathway." (PMID 35845080, 2022). "The administration of resveratrol prevents the alteration in SIRT-1 in type-2 diabetes mellitus and SIRT-1, 2, 3 and SIRT-5 in the type 1 diabetes mellitus rat heart." (PMID 27690014, 2016).
glioblastoma (7 papers, 2019 to 2025). The most malignant astrocytic tumor (WHO grade IV). "Previous study has reported the downregulation of SIRT5 gene in glioblastoma and this deregulation was found associated with poor prognosis." (PMID 36809279, 2023). "SIRT5 was recently reported to be down-regulated in glioblastoma and its down-regulation was associated with poor prognosis." (PMID 32158696, 2020). "Sirtuin 5 plays a crucial role in regulating cellular metabolism, which is often disrupted in cancer cells, leading to increased tumor growth, especially in glioblastoma." (PMID 40710366, 2025). "Experimental results show that knocking down SIRT5 significantly enhances the growth of glioblastoma cells, implying that SIRT5 functions as a tumor suppressor." (PMID 40710366, 2025). "To investigate the clinicopathologic implications of SIRT5 dysregulation in glioblastoma, we performed comprehensive analyses of transcriptomic data and functional verifications using in vitro and in vivo glioblastoma models." (PMID 39201811, 2024). "Knockdown of SIRT5 significantly enhanced glioblastoma cell growth." (PMID 39201811, 2024).
Stroke (7 papers, 2018 to 2025). Sudden impairment of blood flow to a part of the brain due to occlusion or rupture of an artery to the brain. "Enhanced SIRT5 desuccinylation activity was shown to have therapeutic potential in alleviating ischemica-caused mitochondrial damage, resulting in the relief of stroke symptoms." (PMID 40865948, 2025). "It has been shown that SIRT5 expression in microglia increased in the early phase of stroke in MCAO mice." (PMID 40724883, 2025). "It has been shown that SIRT5 promoted ischemia/reperfusion-induced blood–brain barrier damage after stroke." (PMID 40724883, 2025). "Given that SIRT5 is necessary for PKCε-induced ischemic tolerance against stroke, these metabolic pathways are likely mediators of this protection." (PMID 29440987, 2018). "Additionally, T294865 (ASHGV40042838) mapped within 350 kb of another gene ADAMTS2 associating with stroke at 5q35.3, while T297706 (ASHGV40043041) mapped to Sirtuin 5 (SIRT5) within 6 kb at 6p23." (PMID 35754821, 2022). "Therefore, the overexpression of SIRT5 can be considered a therapeutic target in stroke." (PMID 40724883, 2025). "Similarly, lysine succinylation plays a key role in mitochondrial energy metabolism after ischemia during stroke pathology, and SIRT5 acts as a mitochondrially localized NAD+ dependent lysine deacylase that regulates protein succinylation levels and maintains mitochondrial metabolic homeostasis." (PMID 40865948, 2025). "By disrupting the SIRT5–ANXA1 interaction and facilitating SIRT5 clearance, this strategy enhances ANXA1 membrane localization and secretion, ultimately reducing infarct volume, preserving neuronal integrity, and improving neurological outcomes in stroke models—all without apparent toxicity." (PMID 41007413, 2025).
diabetic cardiomyopathy (6 papers, 2024 to 2025). Diabetic cardiomyopathy is a disorder of the heart muscle in people with diabetes. "In diabetic cardiomyopathy, SIRT5 knockout promotes myocardial hypertrophy and diastolic dysfunction in diabetic mice, whereas cardiomyocyte-specific overexpression of Sirt5 alleviates these changes." (PMID 41260100, 2025). "Adding further evidence to this cardiometabolic link, the authors of that study demonstrated that SIRT5-mediated lysine demalonylation of GSTP1 protects cardiomyocytes from pyroptosis in diabetic cardiomyopathy." (PMID 41107644, 2025). "Considering that the roles of SIRT3 and SIRT5 in diabetic cardiomyopathy have been validated 23, 28, we assessed the expression patterns of SIRT2 and SIRT4 in heart tissues." (PMID 39781464, 2025). "We investigated the role of SIRT5 in diabetic cardiomyopathy (DCM) and identified the mechanism regarding lysine demalonylation in this process." (PMID 38169591, 2024).